MUC1 (mucin 1, cell surface associated)
Diseases named in the same sentence as MUC1 in open-access papers (continued):
Sharing a sentence is not in itself a finding about the gene and the disease.
breast carcinoma (continued). "MUC1, a highly glycosylated transmembrane glycoprotein, is overexpressed and aberrantly glycosylated by breast cancer cells resulting in changes in the antigenic profile of the tumour-associated glycoforms." (PMID 18253127, 2008). "For this study we selected seven breast cancer-associated genes [mam, CEA, CK19, PIP, muc1, PSE, Erb (BM only) and EpCAM (PBL only)] known to be over-expressed in metastatic breast cancer compared to control lymph nodes." (PMID 18289390, 2008). "Shed MUC1, comprised largely of tandem repeats, can be detected in the serum of Stage II breast cancer patients." (PMID 18446242, 2008). "T47D breast cancer cells were stably transfected with either siRNA that suppressed MUC1 expression or with a control siRNA." (PMID 18446242, 2008). "In complement to this, MUC1 has been shown to transform rat 3Y1 fibroblasts, and MMTV-MUC1 transgenic mice develop spontaneous mammary tumors, indicating that MUC1 is an oncogene in its own right." (PMID 21655373, 2008). "A week after the final DC injection, the mice were challenged with E3 tumour cells (the murine mammary tumour cell line 410.4 transfected with human MUC1)." (PMID 18253127, 2008). "The MB5 antibody intensively stained MCF7 cells, known for high MUC1 expression, and also reacted well with another breast carcinoma cell line, SkBr3." (PMID 17945015, 2007). "Reaction pattern was similar to previous reports developed in breast cancer employing the CT2 monoclonal antibody directed against the same last 17 aa of the MUC1 cytoplasmic tail." (PMID 17064405, 2006). "To validate the relationship of GATA3 and MUC1 in breast cancer epithelial cell further, we performed an mRNA expression analysis of 36 primary breast carcinomas by means of real-time RT-PCR." (PMID 17078870, 2006). "Initially described as a tumor antigen overexpressed in >90% of breast cancers, MUC1 is now known to be an oncogene with roles in both tumor formation and progression." (PMID 16846534, 2006). "In SAGE (serial analysis of gene expression) studies we observed an intriguing significant correlation between GATA3 and MUC1 mRNA expression in breast carcinomas." (PMID 17078870, 2006). "Recently we performed a cross-platform comparison between SAGE and DNA microarray profiles showing that the ESR1, GATA3, and MUC1 genes are very tightly co-expressed in breast carcinomas." (PMID 17078870, 2006). "The differences between the two breast cancer cell lines in this study suggest that MUC1 oncogenic functions are also subject to cell-specific regulation, and stress the need for understanding the cellular signaling context when interpreting results." (PMID 16846534, 2006). "This characteristic makes the MUC1 protein valuable as a marker in breast cancer diagnostics and prognosis." (PMID 17083744, 2006). "To clarify the role of MUC1 in cancer, we transfected two breast cancer cell lines (MDA-MB-468 and BT-20) with small interfering (si)RNA directed against MUC1 and analyzed transcriptional responses and oncogenic events (proliferation, apoptosis and invasion)." (PMID 16846534, 2006). "Global gene expression studies pointed to a significant correlation in the overexpression of GATA3 and MUC1 genes commonly observed in breast cancer." (PMID 17078870, 2006). "The results suggest that, in early breast cancer, MUC1 immunotherapy is beneficial, and that a larger phase III study should be undertaken." (PMID 16776849, 2006). "CA 15-3 measures the protein product of the MUC1 gene and is the most widely used serum marker in breast cancer." (PMID 16953875, 2006). "Of particular relevance to breast cancer, steroid hormones also stimulate the expression of the MUC1 gene." (PMID 17083744, 2006). "The role of estrogen on MUC1 isoform expression in human breast cancer cells, MCF-7 and T47D, was also analyzed." (PMID 17083744, 2006). "Herein, we report a trial using early stage breast cancer patients and injection of oxidized mannan-MUC1." (PMID 16776849, 2006).
breast carcinoma (continued). "Our study provides evidence indicating that GATA3 is probably a mediator for the transcriptional upregulation of MUC1 expression in some breast cancers." (PMID 17078870, 2006). "It is interesting to note that GATA3 and MUC1 protein expression are positively correlated among normal breast samples as well as in breast carcinomas (τb = 0.44; p = 0.01)." (PMID 17078870, 2006). "CA 15-3 is a serum-based product of the MUC1 gene and is the most widely used serum marker for breast cancer." (PMID 16953875, 2006). "Evidence is accumulating that naturally occurring immunity is present in patients with breast cancer against tumor associated antigens such as HER-2/neu and cdr2, as well as the antigens investigated here, namely MUC-1, cyclin B1 and survivin." (PMID 17129372, 2006). "For example, MUC1 can stimulate Fas-mediated apoptosis, while Muc1 is specifically down-regulated in c-neu-induced mammary tumors." (PMID 16846534, 2006). "In breast cancer tissue, an alternatively spliced form of MUC1, which is completely devoid of repeats was observed." (PMID 16188033, 2005). "Benign mammary epithelium and many breast cancers produce transmembrane mucins, mainly from the MUC1 gene." (PMID 15700031, 2005). "MUC1 is shed into the blood stream and thus has a potential as a tumor marker, as demonstrated in breast cancer." (PMID 16117833, 2005). "C595 mAb has been used in immunoassays for the measurement of soluble MUC1 in breast cancer patients and for in vivo immunoscintigraphy." (PMID 12966437, 2003). "Upon binding to MUC1-positive MCF7 breast carcinoma cells, moreover, the fusion protein activates resting NK cells to tumour cell lysis." (PMID 12966437, 2003). "MUC1 mucin is known to serve as a target molecule in the killing of breast cancer cells by cytotoxic T-lymphocytes (CTLs)." (PMID 11336479, 2001). "A breast cancer cell line, NZK-1, established from one of the cytotoxicity-negative patients, did not express MUC1 and was resistant to killing by CTLs, while control breast cancer cell lines expressing MUC-1 were readily killed by CTLs." (PMID 11336479, 2001). "MUC1-transfected BALB/c breast cancer cell lines 413BCR and 425CCR and the parental cell line (410.4) were labelled with streptavidinylated mouse anti-MUC1 mucin mAb." (PMID 10507767, 1999). "The mucin MUC1 is expressed on breast cancers in an underglycosylated form compared to normal tissues and is therefore a potential target for cancer immunotherapy." (PMID 10206297, 1999). "Amplification of this region had not previously been associated with sarcoma development, but occasional amplification of CACY/S100A6 and MUC1 in 1q21 had been reported for melanoma and breast carcinoma respectively." (PMID 9716033, 1998). "The retention of binding activity to MUC1 antigen on human bladder and breast carcinoma tissue specimens illustrates the potential application of this novel product as an immunodiagnostic and immunotherapeutic reagent." (PMID 9303360, 1997). "With the interaction between the MUC1 C-terminal subunit (MUC1-C) and receptor tyrosine kinases at the cell membrane, the MUC1-C inhibitor has been studied as a potential therapeutic intervention for breast cancer." (PMID 40699805, 2025). "Elevated Gal-4 and its ligand MUC1 in the serum of advanced breast cancer patients may serve as markers for evaluating post-treatment metastasis." (PMID 40134029, 2025). "In breast cancer, targets such as MUC1 and CD70 are more consistently expressed than others that exhibit spatial heterogeneity, and dual-target strategies can mitigate this risk by pairing antigens with nonoverlapping escape mechanisms, such as oncogenes and structural proteins." (PMID 41348261, 2025).
breast carcinoma (continued). "More specifically, the overexpression of MUC1 in pancreatic and breast cancer cells interacts with signaling pathways, such as the MAPK, JAK/STAT, and the PI3K/AKT/mTOR pathways, and VEGF co-receptor, neuropilin-1, to promote the generation of endothelial cell and ectopic blood vessels." (PMID 40699805, 2025). "MUC1-ST, a tumor glycoform of MUC1, interacts with siglec-9 expressed by tumor-associated macrophages, which activates MEK-ERK and contributes to the poorer prognosis of breast cancer." (PMID 40699805, 2025). "Similarly to MUC1 discussed in breast cancer, MUC16 has also been identified to bind to Siglec-9, attenuating T and NK cell functions to help the survival of cancer cells." (PMID 40699805, 2025). "To determine whether this effect also occurs in other cancer types, we detected the phosphorylation of NUMB and PKCζ in cell lines of breast cancer and cervical cancer which overexpress MUC1." (PMID 40349179, 2025). "Biomarkers for breast cancer include MUC1, ER, PR, and HER2." (PMID 40277545, 2025). "These compelling outcomes suggest that Apt‐Td holds considerable promise as a nanoparticle platform for advancing breast cancer treatment.[88b] Furthermore, investigators proposed an innovative strategy involving 1–3 MUC1‐aptamer‐modified DNA tetrahedra for DOX delivery in breast cancer." (PMID 38713753, 2024). "Other reports showed that an increase in the size of the glycocalyx with the MUC1 ecto-domain was sufficient to drive metastatic potential in an in vivo model of breast cancer as well as promoting immune evasion in epithelial cells that had increased MUC1 expression." (PMID 39628991, 2024). "constructed a novel breast cancer vaccine that co-expressed MUC1 and CD80." (PMID 39575257, 2024). "Several mucins have shown clinical promise, including MUC1 (also known as CA 15-3 and KL-6, in breast cancer), MUC4 (pancreatic cancer), and MUC5 (gastrointestinal, pancreatic, gastric cancers); however, only one is FDA-approved and in clinical use, MUC16, also known as CA125 in ovarian cancer." (PMID 39767713, 2024). "Consequently, this study employs the MUC1 promoter to drive the recombinant adenovirus, aiming for more precise targeting of breast cancer cells and thereby enhancing the detection of CTCs." (PMID 39886667, 2024). "As a result, chitosan nanoparticles may be ideal for delivering MUC1 nanobodies to breast cancer cells with high MUC1 levels and decreasing the required dose." (PMID 38341580, 2024). "In addition, MUC1 expression was increased in the presence of estrogens, as has already been described for breast cancer cells." (PMID 39456226, 2024). "To test whether M-DCsTNF can recognize breast cancer cells, we first tested efficacy of M-DCsTNF expressing the chimeric CD66b-Muc1 scFv tagged with a mCherry." (PMID 39105847, 2024). "Similarly, in an in vitro breast cancer model, ErbB2 and MUC1 biCAR-T cells demonstrated potent anti-tumor activity." (PMID 38622705, 2024). "MUC1 is a glycoprotein expressed on the surface of epithelial cells, including breast cancer cells." (PMID 39671082, 2024). "Similarly, MUC1 captured from the sera of patients with breast cancer scarcely bound to PNA, suggesting that most of core 1 was modified with sialic acid or sulfate." (PMID 39337716, 2024). "Additionally, a new electrochemical aptamer-based biosensor has effectively identified breast cancer cells that overexpress MUC1 proteins by using a sandwich formation method with MUC1-specific aptamer assays." (PMID 39685966, 2024). "The antigens HER-2 and MUC-1 are the most well studied antigens in human breast cancer." (PMID 38474142, 2024). "In addition, Proteins such as human epidermal growth factor receptor 2 (HER2), and mucin 1 (MUC1) have been detected in exosomes isolated from breast cancer patients." (PMID 38553754, 2024). "In breast cancer treatment research, MUC1 has emerged as a significant therapeutic target." (PMID 38361923, 2024).
breast carcinoma (continued). "Thus, inhibition of MUC1 by the bioactive agent inhibits breast cancer cell proliferation and metastasis." (PMID 38543147, 2024). "Having shown that ER is stimulated by mast cells in a MUC1-dependent manner, we asked whether this axis plays a role in the increased stem-like properties of mammary cancer cells." (PMID 39349458, 2024). "These nanoparticles were instrumental in developing a unique electrode modification, facilitating the creation of a sensitive impedimetric immunosensor capable of quantitatively detecting canine mammary tumor biomarkers, specifically CA 15–3 and MUC-1, in serum and tissue homogenate samples." (PMID 39031228, 2024). "We hence concluded that mast cell-derived TNF and/or cancer cell TNF triggered by mast cell-derived soluble factors is essential to stimulate the MUC1/estrogen receptor axis and promote the stem-like properties, eventually increasing the aggressiveness of mammary cancer cells." (PMID 39349458, 2024). "Furthermore, the sensor exhibited ease of use and good selectivity in detecting CA 15–3 and MUC-1 in clinical canine serum and tissue homogenate samples, underscoring its efficacy in diagnosing canine mammary tumors." (PMID 39031228, 2024). "However, the clinicopathological use of this subcellular localization of MUC1 in breast cancer is yet to be evaluated, particularly under the advanced framework of current therapeutic options." (PMID 37002293, 2023). "Even though small molecule apigenin was reported to inhibit MUC1-CT dimerisation in the breast cancer cell lines, the inhibitory effect was probably mediated by blocking other direct targets such as heterogeneous nuclear ribonucleoprotein A2 and the oncogenic signalling pathways." (PMID 36810913, 2023). "Besides, the assay also presents low sensitivity for in situ or low stage disease, as the levels of the soluble forms of MUC1 rarely increase at the early stages of breast cancer." (PMID 37455827, 2023). "The mechanism of how glycosylated MUC1 exhibits cytoplasmic localization in tumor cells of some cases of luminal-type breast cancer is presently unknown." (PMID 37002293, 2023). "Additionally, MUC1-CT is also demonstrated to regulate the activity of the nuclear factor kappa B (NF-κB) pathway in breast cancer by cooperating with and stimulating IkB kinase (IKK) family members and NF-κB p65." (PMID 37345016, 2023). "CA 15-3 is a transmembrane glycoprotein of a serum-based derivative of the MUC1 gene and is the most extensively utilized biomarker in observing progressive breast cancer cases that overproduce CA 15-3 in response to chemotherapy, and it is commonly expressed through breast cells." (PMID 37373429, 2023). "In pre-clinical models, dual-targeting CAR-T cells specific to co-expressing HER2 and MUC-1 effectively killed HER2+ breast cancer cells expressing these targets, HER2-redirected CAR-T cells eliminated HER2+ trastuzumab-sensitive tumor cell lines (SKBR3 and BT474)." (PMID 37007133, 2023). "While ER may not directly regulate the MUC1 gene in humans or mice, it does regulate MUC1 mRNA in breast cancer cells via ERα." (PMID 37958878, 2023). "For example, in breast cancer, MUC1 and CD44 overexpression facilitate tumour-EC interactions and promote TEM, with MUC1 overexpression linked to poor prognosis." (PMID 37138793, 2023). "These vaccines specifically bind to MUC1-positive breast cancer cells." (PMID 37514054, 2023). "However, MUC1 is highly overexpressed in a wide range of cancers, including breast cancer, ovarian cancer, pancreatic cancer, colon cancer, and uterine corpus endometrial carcinoma." (PMID 37489369, 2023). "A previous study showed that MUC1 interacts with STAT3 directly in breast cancer." (PMID 36810913, 2023). "Since MUC1 is overexpressed in about 90% of breast carcinomas, its targeting may present a promising therapeutic approach for breast cancer." (PMID 36679991, 2023). "MUC1 was discovered based on the overexpression of this gene in human breast cancers." (PMID 36835130, 2023).
breast carcinoma (continued). "When breast cancer cells and MSCs were simultaneously co-cultured, the therapeutic impact was diminished in vivo due to the upregulation of resistance-related genes (such as MUC1, MYC and BRCA1) in the breast cancer cells after cisplatin pre-treatment." (PMID 37569598, 2023). "Further characterization demonstrated frequent alterations of the MUC1 gene in breast cancers." (PMID 36835130, 2023). "Therefore, our present results suggest that cellular localization of MUC1 with a unique glycosylation is potentially useful as a prognostic indicator of luminal-type breast cancer, as comprehensively reviewed by Pinho and Reis28." (PMID 37002293, 2023). "The MOF derivative was fabricated into a fluorescent nanoprobe, drDNA-BUT-88, which could identify dual tumor biomarkers (i.e., MUC-1 and miRNA-21) in breast cancer cells (MCF-7 cells)." (PMID 35055294, 2022). "In 90% of breast cancer cases, abnormal expression and abnormal glycosylation were found in MUC1." (PMID 35330093, 2022). "Although these autoantibodies have been known as breast cancer biomarkers, the problem is that autoantibodies against aberrantly glycosylated MUC-1 are also present in healthy people and benign diseases, which makes it hard to differentiate between cancer and healthy titers." (PMID 35000604, 2022). "Proof-of-concept for MUC1 as an effective CAR-T target is evident in breast cancer, where TAB004 (mAb targeting glycosylated MUC1), engineered into CAR-T format, has shown target-specific cytotoxicity, cytokine secretion and reduced tumour burden in a xenograft model." (PMID 35158772, 2022). "Finally, we analyzed the prognostic role of CA15-3, a serum marker derived from MUC1 and widely used for breast cancer clinical management." (PMID 36430448, 2022). "Importantly, to eliminate the interference of cell model, we knocked out MUC1 in another breast cancer cell line MDA-MB-231 and replicated the experiments." (PMID 35970845, 2022). "A MUC1-directed CAR T cell approach concomitantly targeting tumor necrosis factor-related apoptosis-inducing ligand receptor 2 (TR2) expressed on MDSCs demonstrated enhanced antitumor tumor activity in breast cancers enriched with MDSCs and TME remodeling." (PMID 35741103, 2022). "The mucin 1 (MUC1) gene was discovered based on its overexpression in human breast cancers." (PMID 36230728, 2022). "For example, aberrantly glycosylated MUC1 is overexpressed in breast cancer and in other cancers." (PMID 35743163, 2022). "In summary, the present study reports a novel model in which MUC1/ATAD3A/Pink1 axis-mediated mitophagy plays a crucial role in maintaining the malignant properties of cancer cells, providing a novel therapeutic target for the management of MUC1-positive breast cancers." (PMID 36289190, 2022). "We also show that combined inhibition of MUC1 and mitophagy could represent a novel therapeutic strategy for MUC1-positive breast cancers." (PMID 36289190, 2022). "At the same time, MUC1 is also an important marker for monitoring metastatic breast cancer." (PMID 35330093, 2022). "SZU251 + MUC1 + Al displayed high efficacy and low toxicity in the treatment of breast cancer." (PMID 36499455, 2022). "For example, the peptide vaccine oxidized-mannan-MUC1 showed a significantly reduced recurrence rate in the verum versus the placebo group (12.5% vs. 60.0%) among patients with stage II breast cancer in a pilot phase III study with a long-term follow-up of up to 15 years." (PMID 35389164, 2022). "Similarly, GO-201 resulted in necrosis, loss of tumorigenicity, and prolonged regression of tumor growth in MUC1-positive breast cancer cells in vitro as well as in the mice model." (PMID 35389164, 2022). "(iii) Natural MUC1 Abs from breast cancer patients reacted more strongly with GalNAc peptides than with the naked 60-mer peptide, indicating that a MUC1 glycopeptide could be a better vaccine." (PMID 35158915, 2022).